FOXP3 (forkhead box P3)
Diseases named in the same sentence as FOXP3 in open-access papers (continued):
Sharing a sentence is not in itself a finding about the gene and the disease.
bladder cancer (continued). "Likewise, the expression of FOXP3 is inversely correlated with long-term survival in bladder cancer." (PMID 39668835, 2024). "We hypothesized that FOXP3 may regulate a gene program that induces immune resistance in bladder cancer." (PMID 39099201, 2024). "We showed that FOXP3 is critical in the ability for IFNγ to activate PD-L1 in bladder cancer cells." (PMID 39099201, 2024). "Here, we investigated the relationship between FOXP3 and PD-L1 in bladder cancer." (PMID 39099201, 2024). "Similarly, we noticed that the ratio of Treg cells (CD25+ FOXP3+) in bladder cancer tissues was also downregulated after the administration of α-TIGIT." (PMID 35069212, 2021). "Taken together, Foxp3 expression in tumor cells can suppress intratumoral immunity in bladder cancer, which might be mediated though HIF-1α and its downstream VEGF production." (PMID 27557492, 2016). "In the present study we demonstrated that the Foxp3 can enhance HIF-1α protein expression through decreasing ubiquitin-mediated proteasomal degradation in bladder cancer cells and influences VEGF signaling and intratumoral immunity, contributing an unfavorable prognosis in bladder cancer." (PMID 27557492, 2016). "In invasive human bladder cancer, Foxp3 expression is a worse prognostic factor for overall survival, in which the presence of Foxp3Δ3 isoform protein may contribute to in vitro spheroid formation in SW780 cells and larger tumor growth in mice, as well as chemoresistance." (PMID 27557492, 2016). "On the other hand, both FGFR signaling and VEGF signaling can be regulated by HIF-1α expression in bladder cancer, which may reduce the correlation of Foxp3 expression with tumor stage and grade, because both of two signaling represent divergent molecular pathways in urothelial carcinogenesis." (PMID 27557492, 2016). "Also in agreement with our results, FOXP3+ infiltrates have been observed in bladder carcinomas, although these have not yet been associated with poor prognosis." (PMID 26398410, 2015). "As IFNγ is a key regulator for PD-L1 expression, we tested the ability for IFNγ to induce expression of endogenous FOXP3 and PD-L1 in HT1376, T24, and SW780 bladder cancer cell lines by flow cytometry." (PMID 39099201, 2024). "As expected, we noticed that IL-32 was also colocalized with FOXP3 and TIGIT in murine bladder cancer tissues." (PMID 35069212, 2021). "To verify the expression of IL-32 in Treg cells in bladder cancer tissues, we analyzed the abundances of IL-32, TIGIT, FOXP3, and CD25 in the TCGA and GTEx as previously reported." (PMID 35069212, 2021). "On average, 30.13 ± 2.17% of lymphocytes in draining lymph nodes from patients with bladder cancer were positive for both CD4 and FOXP3 molecules." (PMID 33305045, 2020). "We found that the number of CD4+, CD8+, CD25+, FoxP3+ and CD20+ TILs and the frequency of blood Tregs changed with the progression of the urinary bladder cancer." (PMID 26927070, 2016). "An increased frequency of intratumoral FOXP3+ Tregs and inhibitory cytokines such as IL-10 and TGF-β was noted in bladder cancer patients compared to the healthy population." (PMID 27221038, 2016). "FOXP3-positive T cells and increased IL10 levels are present in human bladder cancers and in the mice models." (PMID 22013484, 2011). "We found that IL-32 was colocalized with FOXP3 and TIGIT in clinical bladder cancer samples." (PMID 35069212, 2021). "Bladder cancer-infiltrating CD4+FOXP3+ T cells did not produce IL-2 or IFN-γ even upon stimulation, and readily suppressed autologous CD4+ effector T cells, confirming that tumor-infiltrating CD4+FOXP3+ T cells act functionally as T regs." (PMID 31811337, 2020). "Taken together, Foxp3 can be detected to be able to bind with HIF-1α protein, particularly upon hypoxia or MG132 treatment and enahnce HIF-1α protein expression through decreasing ubiquitin-mediated proteasomal degradation in human bladder cancer cells." (PMID 27557492, 2016).
bladder cancer (continued). "And in yet another clinical trial in which bladder cancer patients were treated with ipilimumab, it was found that treatment-induced no consistent changes in Treg frequencies (CD4+Foxp3+, CD4+Foxp3+ICOShi, or CD4+Foxp3+ICOSlo T cells)." (PMID 23653893, 2013). "In muscle-invasive bladder cancer, some evidence supports a correlation between invasion of Foxp3+ T cells into cancer tissue and patient prognosis, but a relationship between Foxp3+ T cells and the recurrence of NMIBC, which is an earlier stage of bladder cancer, has not been evaluated previously." (PMID 30261082, 2018).
graft versus host disease (32 papers, 2011 to 2025). An immune system disorder that occurs after allogeneic hematopoietic stem cell transplant and is a reaction of donor immune cells against host tissues. "CD8+Foxp3+Tregs have been identified during graft versus host disease (GVHD) reactions and regulate allotransplant-associated immune responses by lowering its severity, but are less potent immunosuppressors than conventional CD25+CD4+Foxp3+Tregs." (PMID 41009359, 2025). "In the setting of haematopoietic stem cell transplantation, several studies demonstrated that the occurrence and severity of graft versus host disease (GvHD) can be associated with reduced levels of Foxp3+CD4+CD25+ Tregs." (PMID 36875063, 2023). "Moreover, few studies have reached the conclusion that high numbers of circulating CD4 + CD25 + FoxP3+ cells are associated with reduced incidence of graft versus host disease (GVHD) after allogeneic stem cell transplantation." (PMID 34640606, 2021). "Interestingly, a few studies have reached the conclusion that high numbers of circulating CD4 + CD25 + FoxP3+ cells are associated with reduced incidence of graft versus host disease (GVHD) after allogeneic stem cell transplantation." (PMID 34640606, 2021). "The treatment results in diminished induction of graft-versus-host disease (GvHD) due to enhancement of Foxp3 expression and further Tregs expansion." (PMID 34281195, 2021). "CD101 is expressed on CD4+ and CD8+ T-cells, dendritic cells and monocytes, and appears to alter CD4+/CD25+/FOXP3+ T regulatory cell (Treg) function based on both a murine graft-versus-host disease model, and through IL10 secretion from human dendritic cells." (PMID 29108000, 2017). "This phenomenon of IFNγ-secreting Foxp3+ cells is further supported and extended in a recent study identifying that IFNγ secretion by Foxp3+ cells was necessary for their regulatory function in a model of graft-versus-host disease." (PMID 23345540, 2013). "In a mouse model of graft versus host disease Ma and colleagues noted an increased proliferation of FoxP3+ regulatory T cells upon transfer of Stat1−/− splenocytes into irradiated hosts." (PMID 22719255, 2012). "While clinical data for PD-1KO CAR Tregs are not yet available, preclinical studies have shown that these cells maintain Foxp3 expression and suppressive function for at least three weeks post-transfer in a xenogeneic graft-versus-host disease (xenoGVHD) model." (PMID 41158870, 2025). "CD4+Foxp3+ regulatory T cells (Tregs) are immunosuppressive cells that play a critical role in maintaining immune homeostasis and preventing autoimmune diseases, including allergic diseases, graft-versus-host disease (GVHD), and transplant rejection." (PMID 41383603, 2025). "As FOXP3+ iTregs can be readily expanded in large quantities from naïve T cells ex vivo, they have potentially enormous clinical application in autoimmune disorders and graft-versus-host disease." (PMID 38891024, 2024). "The authors reasoned that IFNγ produced by FOXP3+ Treg cells has essential immunosuppressive functions that are required for the prevention of experimental graft-versus-host disease, which hints at a more universal function of this cytokine beyond its role in classical Th1-type immune responses." (PMID 35225986, 2022). "Indeed, in vivo administration of hypomethylating agents (HMA) induce Foxp3+ Tregs expansion leading to immune suppression, and attenuates graft-versus-host disease." (PMID 33648567, 2021). "It upregulates the expression of Foxp3 T cells and prevents Graft versus host disease (GVHD) in an experiment in a mouse model." (PMID 39273326, 2024). "In a graft-versus-host disease (GVHD) model, CTLA-4Ig/CD40L Ab treatment prevented the expansion of host-reactive donor T cells but promoted proliferation of Foxp3+ Tregs." (PMID 26042125, 2015).
graft versus host disease (continued). "Enhanced Treg production following IUT, particularly of CD62L+ CD25+ FOXP3+ Tregs, protects against graft-v-host disease, and together with putative Breg (expressing IL10, IL5, IL6, FOXP3, TGF-β), probably influenced the resulting tolerogenic or immunogenic responses." (PMID 37226255, 2023). "But VIP can act directly on the Teff cells – culture of CD25−Foxp3− Teff with VIP induces their differentiation into CD25+Foxp3+ Treg that express high levels of IL-10 and CTLA4 and are protective in a mouse model of graft versus host disease (GVHD)." (PMID 24550907, 2014). "Unlike CD4+Foxp3+ Tregs, these cells suppressed T cell responses regardless of Foxp3 expression, and they also played a role in the spontaneous liver tolerance and autoimmunosuppression of stimulatory graft-versus-host disease (GVHD) with a lupus-like syndrome." (PMID 31402273, 2019). "Additionally, other have used an acute inflammation model, acute graft-versus-host disease (GVHD) mouse model, to document that TNFα in serum selectively activated Treg and induced Treg proliferation and function without impacting CD4+Foxp3− T cells." (PMID 30631042, 2019).
leukemia (32 papers, 2009 to 2025). A malignant (clonal) hematologic disorder, involving hematopoietic stem cells and characterized by the presence of primitive or atypical myeloid or lymphoid cells in the bone marrow and the blood. "Our previous study described the association between the expression levels of the PD-1 and FOXP3 genes and the OS in the BM leukemia cells AML patients based on TCGA database and described the expression pattern correlated with the poor OS." (PMID 40236710, 2025). "To the best of our knowledge, we first explored the association between the expression levels of the PD-1 and FOXP3 genes and the OS in the BM leukemia cells AML patients based on the TCGA database and described the expression pattern correlated with the poor OS." (PMID 36591503, 2022). "For instance, the poly(A) signal alters from AAUAAA to AAUGAA in FOXP3 leads to an immune dysregulation syndrome; widespread poly(A) site switch to intronic loci inactivates tumor suppressor genes in leukemia and extensive APA were found associated with leukemia at the single cell level." (PMID 37789388, 2023). "We ask the question whether a higher FOXP3 mRNA expression in recipient CD4+ T cells obtained from peripheral blood prior to myeloablative conditioning was associated with an increased risk of posttransplant leukaemia relapse." (PMID 36051013, 2022). "Similar to findings in the MLL-AF9 leukemia model, we observed that Il1rl1+Foxp3+ Tregs were significantly reduced in the spleen and liver of BC281-treated mice compared to those receiving BC462." (PMID 40659660, 2025). "γδ T cells are essential for anti-leukemia function in immunotherapy, however, γδ T cells have different functional subsets, including regulatory cell subsets expressing the Foxp3." (PMID 36591503, 2022). "Consistent with our finding, several lines of evidence have recently highlighted the roles of FOXN3, FOXO3, FOXO4, and FOXP3 in leukemia." (PMID 36292640, 2022). "first noted increased CD4+CD25+FoxP3+CTLA-4+ Tregs occurring alongside leukemia development in the Eμ-TCL1 transgenic mouse model of CLL." (PMID 35979372, 2022). "Our studies showed that CML-derived EVs controlled biology of Treg, as they increased suppressive function and forkhead box P3 (Foxp3) level in Treg, which are beneficial for leukemia progression." (PMID 33801964, 2021). "DNR-induced CD4+CD25+Foxp3+ T cells were shown to act as Tregs through the complete inhibition of leukemia-specific IFN-γ production by both CD4+ and CD8+ T cells." (PMID 29312358, 2017). "Given the undisputed role of IDO1 in activating and stabilizing Treg cells, we measured intracellular FoxP3 levels after culturing allogeneic naïve T cells with IDO-expressing leukemia blasts." (PMID 24903009, 2014). "In recent studies, leukaemia cells from patients with ATLL strongly expressed FoxP3, a specific marker for Treg cells." (PMID 19557183, 2009). "Interestingly, according to The Cancer Protein Atlas, leukemia cells prefer an increment in FOXP3 expression compared to other types of cancer." (PMID 40746879, 2025). "Consistently, our data also demonstrate an increasing trend in the Foxp3+ T-cell subsets in the Vδ1 and Vδ2 T-cell populations, which may be related to the primary reason for leukemia immunosuppression." (PMID 40236710, 2025). "There is evidence that the reduction of FOXP3 increases the survival rate in leukemia patients, and targeting this transcription factor could be a promising therapeutic strategy, even in solid tumors." (PMID 40746879, 2025). "In addition, increased CD4+CD25+FOXP3+CTLA-4+ Tregs occurring alongside leukemia development were described in the Eμ-TCL1 transgenic mouse model of CLL." (PMID 39335199, 2024). "Our results also demonstrate an increasing trend in the Foxp3+ T cell subsets in the Vδ1 and Vδ2 T cell populations, which might be related to the primary reason for leukemia immunosuppression." (PMID 36591503, 2022).
leukemia (continued). "Given that FOXO4 and FOXP3 were highly expressed in combination in precursor T lymphoblastic leukemia, acute promyelocytic leukemia, leukemia, and acute myeloid leukemia, we explored the correlation of these two genes in the GEPIA2 database and found that they were positively correlated in AML." (PMID 36292640, 2022). "More importantly, AML patients containing higher PD-1+Foxp3+ γδ T cells had lower OS, which might be a potential therapeutic target for leukemia immunotherapy." (PMID 36591503, 2022). "In addition, FOXK2, FOXL1, FOXO1, and FOXP3 were differentially expressed in at least six subtypes of leukemia." (PMID 36292640, 2022). "We further characterized the leukemia cells by analyzing their Foxp3 and CCR4 expression." (PMID 35906240, 2022). "Recent investigations have focused on Foxp3+ regulatory T cells (Tregs) as a therapeutic tool, based on its regulatory functions in GvHD pathogenesis and their instrumental role in mitigating GvHD severity while preserving graft-versus-leukemia (GvL) activity." (PMID 32117306, 2020). "Further research supports the idea that HMAs post-HSCT can reduce GVHD while preserving the graft-versus-leukemia (GVL) effect, primarily by promoting the expansion of regulatory T cells and increasing FOXP3+ Tregs." (PMID 39253078, 2024). "Our results indicate that the phenotype of Tregs changes during the course of leukemia to establish a subpopulation of CD4+, FoxP3+, LAG-3+, CD69hi, and surprisingly, CD44lo and CD25lo cells." (PMID 35296093, 2022). "In this model, FoxP3+ Treg depletion resulted in expansion of CD8+ effector cells and leukemia clearance." (PMID 35979372, 2022). "The FoxP3+ and CD25HIGH TREG levels were significantly correlated both in patients with untreated leukemia and during chemotherapy-induced cytopenia (p < 0.001)." (PMID 20618967, 2010). "IL-2 is required for T-cell activation, differentiation, and survival but can also be favorable as IL-2 selectively can restore the immunosuppressive function of FoxP3 Tregs without activation of T-cells or abrogation of anti-leukemia effects." (PMID 31105702, 2019). "For example, GATA1 partners with HNF1 in hematopoietic progenitor cells; with PPARA:RXRA in leukemia; with SRF, CDX and FOXP3 in primary T-cells; with SRY, NKX2-1, FOXF1, OCT4 and ZBTB16 in differentiated ESCs and with TAL1:TCF3 motif co-occurring in various fibroblasts." (PMID 30142147, 2018). "DC-loaded with DNR-treated AML cells were more efficient than DC-loaded with ARA-C-treated cells not only, as expected, in inducing leukemia-reactive CD8+ T cells, but also in increasing the frequency of CD4+CD25+Foxp3+ T cells (11.70 ± 4.15 versus 5.97 ± 3.10%, respectively; p < 0.05)." (PMID 29312358, 2017). "The slightly elevated Foxp3 expression in the CD4+CD25− population of ATL patients may reflect the presence of leukemia cells." (PMID 19654865, 2009). "Co-culture with IFN-γ-activated AML blasts resulted into an increase of FoxP3-expressing bona fide Treg cells, when compared with cultures maintained in the absence of leukemia blasts or with those nurtured with a polyclonal stimulus, such as PHA, and IL-2, a Treg growth factor." (PMID 24903009, 2014). "It is controversial whether ATL is a leukemia of FoxP3+ Treg cells or not." (PMID 22647666, 2012).